IL10 (interleukin 10)
Diseases named in the same sentence as IL10 in open-access papers (continued):
Sharing a sentence is not in itself a finding about the gene and the disease.
tumor (continued). "The significance of interleukin 10 (IL-10) within the tumor microenvironment is debated because it is dependent of the malignant cells, tumor-infiltrating macrophages and lymphocytes." (PMID 22353218, 2012). "In particular, IL-10 is highly expressed in tumor cells and its expression is directly proportional to the development of HPV-positive CC, suggesting an important role of HPV proteins in the expression of IL-10." (PMID 22220169, 2012). "But there is a body of evidence which shows that IL-10 can actually assist in antitumor immune responses in a variety of tumor models, including lung cancer." (PMID 22899945, 2012). "This was associated with increased Treg numbers and expression of IL-10 and TGF-β1 in tumor-draining lymph nodes and at the tumor site." (PMID 22674057, 2012). "These cells have been found in the tumor milieu and mediate immunosuppression by secreting immunosuppressive interleukin-10, decreasing CD4+ and CD8+ T-cell viability, and attracting Treg." (PMID 23056925, 2012). "It has been shown that TAM and myeloid populations in the spleen of HPV16 tumor-bearing mice are important for tumor growth via stimulation of specific regulatory T cells, in a mechanism partially dependent on IL-10 expression by TAM." (PMID 22220169, 2012). "Sunitinib-treated mice revealed a modification of their tumor microenvironment characterized by a reduced expression of immunosuppressive cytokines (IL-10, TGFβ) and inhibitory molecules (PD-1, CTLA-4)." (PMID 23320019, 2012). "This immune dysregulation should be proved by altered IL-6/IL-10; iii) the decrease in IL-6 levels and increase in IL-10 levels are evidence of an altered host immune response to the tumour, confirmed by cell activation due to BCG." (PMID 23181118, 2012). "In our study MELOE-1 derived specific CD4 T cell clones exhibited a high ratio IFN-γ/IL10, thus favourable to the development and the persistence of anti-tumour responses." (PMID 23284752, 2012). "Tumor-derived soluble factors such as IL-10, TGF-β, and VEGF suppress effector cells either directly or indirectly by disruption of dendritic cell (DC) differentiation, migration and antigen presentation." (PMID 22592077, 2012). "High IL-10 expression in tumor cell areas (p = 0.018) and stromal areas (p = 0.003) in the primary tumors predicted mortality, whereas high staining intensity in stroma of the metastases was borderline associated (p = 0.057)." (PMID 22353218, 2012). "In CC tumour models where IL-10 suppresses the immune response and increases tumour growth, the production of IL-10 is much lower." (PMID 22220169, 2012). "The cytokine milieu, although supporting tumor growth, is thus rich in TGFβ and IL-10, conditions that favor development of Treg." (PMID 23056925, 2012). "MR and Mgl-1/2 recognize specifically highly glycosylated molecules such as mucins present in the tumor microenvironment, leading to the expression of the immunoregulatory cytokine IL-10 that favors the attraction of Treg cells." (PMID 23316105, 2012). "Several molecules/factors secreted by TAMs such as MMP-9, IL-23, IL-10 facilitate tumor cell proliferation thereby limiting the cytotoxicity of the microenvironment." (PMID 23316105, 2012). "IL-10 is commonly regarded as an anti-inflammatory, immunosuppressive cytokine that favors tumor escape from immune surveillance." (PMID 22778768, 2012). "For instance, human tumor-infiltrating CD8+/CD28- regulatory T cells secrete IL-10, TNF-α, and IFN-γ, express FOXP3, and suppress the proliferation of CD8+ effector T cells." (PMID 23272178, 2012). "The role of cytokines can be either pro-inflammatory, tumor-promoting (interleukins IL-6, IL-12 family, IL-23) or tumor-inhibiting, as is the case of IL-10." (PMID 24710489, 2012). "Tumor-bearing rats showed significantly higher serum levels of both sIL-2R and IL-10 than did non-tumor-bearing rats prior to the operation (P<0.05)." (PMID 23139816, 2012).
tumor (continued). "On the basis of above discussion, we suggest a model for p80HT activation of the IL-10-Stat3 signaling pathway to promote plasma cell expansion and tumor development by regulating the generation, proliferation and survival of plasma cells." (PMID 22642622, 2012). "They suppress effector cells mainly through contact-dependent mechanisms, although Treg secretion of transforming growth factor-β (TGF-β) and IL-10 have also been shown to inhibit tumor-specific CTL cytotoxicity in vivo." (PMID 23029485, 2012). "Inhibition of NF-κB by the IL-10 contributes to the anti-tumor effects through the activation of caspase-3 and apoptosis in Colon26-bearing mice." (PMID 22567084, 2012). "Alternatively, p-STAT3 promotes tumor cells to produce multiple oncogenic cytokines, such as IL-10, which in turn activates STAT3 signaling through a positive feedback loop and inhibits functional DC stimulation." (PMID 22911830, 2012). "The interleukin 10 (IL-10) is well known as an anti-tumor factor as well as an anti-inflammatory factor." (PMID 22567084, 2012). "Among the most well-known and best characterized tumor-derived immunosuppressive molecules are interleukin-10 (IL-10), transforming growth factor-beta (TGF-β), and vascular endothelial growth factor (VEGF)." (PMID 22592077, 2012). "The cytokine signature of increased IFNγ and reduced IL-10 in the tumor further facilitates antitumor activity." (PMID 22815789, 2012). "The expression of TGF-beta, IL-10 and Ki67 were recorded in tumor cell areas and adjacent tumor stromal areas." (PMID 22353218, 2012). "High levels of IL-10 within the tumor microenvironment have been shown to favor tumor rejection by enhancing cytotoxicity of T lymphocytes." (PMID 22328825, 2012). "Distribution of TGF-β, IL-10 and Ki67 in tumor cell areas and tumor stromal areas and their corresponding metastases." (PMID 22353218, 2012). "Colon inflammation has been shown to predispose to development of inflammation-associated neoplasia in both humans and in mouse models of IBD, including Il10−/− mice." (PMID 22848611, 2012). "Except for TGF-β, the expression of COX-2, IL-10 and Ki67 in this study was higher in tumor stromal areas than in tumor cell areas." (PMID 22353218, 2012). "There has been significant progress in determining the regulation and mechanism of IL-10 function since its discovery, particularly with regard to its role in tumor immunology." (PMID 22778725, 2012). "We also found that the high expression of IL-10 in TAM was associated with poorly differentiation, which highlighted a significance role of IL-10 secreted by TAM in tumor aggressiveness." (PMID 21595995, 2011). "So it is important to isolate TAM from tumor cells to study the role of IL-10 in the progression of cancer." (PMID 21595995, 2011). "The results suggest that MHC class IIlow TAMs contribute to tumor progression via IL-10/TGF-β-mediated suppression of T cell activation." (PMID 21813021, 2011). "In tumor-bearing mice only IL-10 and GM-CSF levels were significantly elevated when compared to naïve mice." (PMID 21901144, 2011). "IL-10 inhibits the releases of IL-12p70, and is often considered as unfavorable for promoting anti-tumor immunity." (PMID 21689407, 2011). "Interleukin-10(IL-10) is a potent immunosuppressive cytokine, which can be secreted from both primary tumor and stromal cells." (PMID 21595995, 2011). "Th1 cells classically produce IFN-γ, tumor necrosis factor-beta (TNF-β) and interleukin-10 (IL-10), and mediate cellular immune responses against tumor cells, intracellular viruses and bacteria through activation of macrophages and cytotoxic T-cells." (PMID 19622600, 2011). "In the tumor microenvironment, monocytes differentiate into a distinct macrophage phenotype, which is characterized by the production of high level of IL-10." (PMID 21595995, 2011).
tumor (continued). "For example, studies in patients with HCC reveal that two distinct populations (HLA-DRhigh and HLA-DRlow IL-10+) of monocytes/MΦ exist within different regions of the tumor, which modulate T cell activation via different mechanisms." (PMID 21813021, 2011). "In the current study, we investigated the effects of IL-22, a member of the IL-10 cytokine family, on human RCC cell line A498 cells in vitro and in vivo and studied the possible mechanisms underlying the anti-RCC tumor effects of the cytokine." (PMID 21625390, 2011). "We also assessed the frequency and cell number of NKp46+ cells producing IFN-γ or IL-10 in naïve mice and following tumor challenge." (PMID 21484786, 2011). "Amongst ten analyzed pro/anti-inflammatory cytokines, only IL-10 and GM-CSF levels were elevated in the tumor-bearing brains comparing to naïve mice." (PMID 21901144, 2011). "STAT3 expression is often found in tumors and tumor-infiltrating macrophages and is induced by IL-6 and IL-10." (PMID 22176642, 2011). "Similar to the effects on M2 macrophages, tumor cell-derived cytokines and mediators, such as IL-10, TGF-β, and PGE2, have immunosuppressive effects on the infiltrating lymphocytes." (PMID 24213108, 2011). "Tumor T lymphocytic infiltrates from mCCL21-vault treated mice had increased intracytoplasmic IFNγ and reduced IL-10." (PMID 21559281, 2011). "Previous reports have also shown that TAMs produce high levels of IL-10, exhibit little cytotoxicity for tumor cells." (PMID 21595995, 2011). "So it is important to isolate TAM from tumor cells to study the role of IL-10 in the progress of cancer." (PMID 21595995, 2011). "The evidence provided supports IL-10 involvement in tumor rejection and allograft rejection in humans, and suggests that this cytokine defies its reputation of having solely anti-inflammatory properties." (PMID 21992116, 2011). "HLA-DRhigh and HLA-DRlow IL-10+ monocytes/MΦ have also been identified in different regions within tumor tissues, where they mediate T cell anergy through PD-L1 and increase tumor cell migration and invasion." (PMID 21813021, 2011). "Our results showed that the un-stimulated tumor cells only secreted IL-10 when cultured for 24 and 72 h in complete RPMI medium." (PMID 21269511, 2011). "On the other hand, the expressional levels of IL-10 are extremely low and/or negligible in normal tumour cell lines." (PMID 21791113, 2011). "We showed recently that tumor skewed IL10-producing M2 macrophages can fully revert to IL12-producing M1 macrophages following interaction with CD4+ Th1 cells or with CD40-L-expressing cells in the presence of IFNγ." (PMID 22176642, 2011). "In conclusion, our data suggested that systemic treatment of Pam2 lipopeptides promoted IL-10 production and T reg function, which suppressed the effective induction of anti-tumor immunity in vivo." (PMID 21533081, 2011). "We previously showed that CXCL12 orchestrates the recruitment of pre-DC2s and protects them from tumor macrophage IL-10-promoted apoptosis, thereby contributing to the immunosuppressive network within the tumor microenvironment." (PMID 21410972, 2011). "In IL-10−/− mice, neoplasms develop that resemble human adenocarcinomas, which has been described previously." (PMID 21799775, 2011). "Secretion of IL-12p70 by DCs augments and directs the expansion and differentiation of tumour specific Th1 responses while high levels of IL-10 secretion preferentially leads to the expansion of immunosuppressive T regulatory cells." (PMID 22125641, 2011). "Tolerogenic DC can be induced by tumor- or immune cell-derived factors like IL-10 and are critically involved in tumor progression." (PMID 21818385, 2011). "Increased resistance to cytotoxic molecules, such as perforin, decreased tumour antigen expression and secretion of immunosuppressive factors, such as IL-4, IL-10 and transforming growth factor-β1 are alternative (or concurrent) mechanisms of immune escape." (PMID 21811598, 2011).
tumor (continued). "On the contrary, the number of IL-10-producing NK cells was higher in WT mice after tumor inoculation." (PMID 21484786, 2011). "The proportion of IL-10-expressing MΦ in the MHC class IIlow TAM subset was approximately 42% on Day 10 post-tumor inoculation, whereas the proportion in the MHC class IIhi TAM subset was only around 18%." (PMID 21813021, 2011). "We can predict tumor size, lymph nodal metastasis and pleural invasion through.IL-10 expression in isolated TAM." (PMID 21595995, 2011). "Another effect of IL-10 neutralization in mice was the decrease in tumor cell infiltration by B cells and reduction of the B cell numbers in peripheral lymph nodes." (PMID 20525400, 2010). "We also performed RT-PCR analysis using primers specific for IL-10, IL-17, and IL-23, cytokines that are involved in the tumor-related inflammation." (PMID 20544025, 2010). "Other factors secreted by tumours, such as Interleukin-10 (IL-10) and transforming growth factor-β (TGF-β), are attractive targets for knockdown using oncolytic HSV." (PMID 20836854, 2010). "IL-10 is an anti-inflammatory, immunosuppressive cytokine that is involved in tumour escape from immune surveillance." (PMID 20836854, 2010). "Nevertheless, the mice treated with anti-IL10/IL10R antibodies had even slower tumor growth, with a significance of p = 0.0005." (PMID 20525400, 2010). "Altogether, our results point to IL-10 as one of the elements involved in tumor immune evasion via T cell regulatory phenotype induction." (PMID 20525400, 2010). "M2 macrophages secrete several cytokines, among them IL-10, which has been shown to play a role in T cell suppression by tumor macrophages in other tumor models." (PMID 20525400, 2010). "Analysis by cytokine array showed a negligible signal for IL-10 and IL-9 in a pool of three splenic tumour tissue samples, which was equivalent to NSC splenic samples." (PMID 20161707, 2010). "Here, we find that the activated mast cells remodel tumor inflammatory microenvironment by upregulating CCL2, IL-10 and IL-13, which are associated with the migration and function of MDSCs, respectively." (PMID 20111717, 2010). "In this work, we first showed that the CD45+ tumor fraction expressed different cytokines, among them IL-10, TNFα and TGFβ." (PMID 20525400, 2010). "It has also been reported that human CD4+ regulatory NKT cells can suppress the expansion of tumor antigen-specific CTLs via Th2 cytokines such as IL-4 and IL-10." (PMID 20052413, 2010). "IL-10 is a multifunctional cytokine with both immunosuppressive and anti-angiogenic functions, consequently resulting in both tumor-promoting and tumor-inhibiting properties." (PMID 20735825, 2010). "Our results indicate that, at least in part, IL-10 facilitates tumor growth by inducing T cell regulatory phenotype and therefore inhibiting T cell anti-tumor activity." (PMID 20525400, 2010). "We also analyzed the ability of TyrTCR Tregs to influence cytokine production (e.g. IFN-γ, IL-2, and IL-10) when co-incubated with a tumor infiltrating cell line (TIL1235) and peptide pulsed APCs." (PMID 20668510, 2010). "On the other hand, anti-angiogenic effects of IL-10 are supposed to play a protective and preventive role against tumor." (PMID 20553628, 2010). "Significant reduction in tumor growth was also observed when anti-IL-10/IL-10R antibody treated mice were compared with tumor growth in mice treated with irrelevant IgG in the same amount, and doses, as the specific antibodies." (PMID 20525400, 2010). "Our data shows that in the HPV16 TC-1 tumor mouse model, IL-10 produced by tumor macrophages induce regulatory phenotype on T cells, an immune escape mechanism that facilitates tumor growth." (PMID 20525400, 2010). "Tumor cells released substantial quantities of TGF-β, PGE2 and IL-10, which were associated with a decrease in CD8+ T cells within the tumor." (PMID 21437225, 2010).
tumor (continued). "In the tumor microenvironment IL-10 has detrimental effects on immune responses as it promotes the polarization of M2 macrophages inhibits the differentiation of Th1 lymphocytes while favouring that of Treg." (PMID 21331365, 2010). "To further test this, we have pretreated monocytes with JSI-124, for 1 hour prior to their co-culturing with the tumor cells, or incubation with either IL-10 or tumor cell's conditioned media." (PMID 19718269, 2009). "AOM-treated Il10−/− mice showed a dramatic increase in tumor penetrance and multiplicity compared to WT mice." (PMID 19551144, 2009). "According to Argarwal and colleagues, early stage of oral SCC expressed mainly INF-γ and IL-2 genes (Th1 responses), whereas the advanced stage tumours presented IL-4 and IL-10 expression (Th2 response)." (PMID 20049171, 2009). "An antibody-IL10 fusion protein of irrelevant specificity in the mouse exhibited a reduced tumor uptake in the same animal model." (PMID 19781067, 2009). "With the tumor progressed, this picture changed: IL-10 production increased and TNF-α and IFN-γ production decreased, and the animals showed extensive fungal dissemination." (PMID 19534779, 2009). "With the tumor progression, this picture changed: IL-10 production increased and IFN-γ and TNF-α release decreased; furthermore, there was extensive fungal dissemination." (PMID 19534779, 2009). "Our results demonstrated that the mice produced more IFN-γ and TNF-α and less IL-10, and also exhibited fungal clearance, at the beginning of tumor evolution." (PMID 19534779, 2009). "In contrast, using the AOM/Il10−/− model, we observed a strong correlation between inflammation score and tumor multiplicity." (PMID 19551144, 2009). "It has been stated that abnormal elevated levels of Th2 cytokines such as IL-10 are able to skew an immune response that favors tumor growth." (PMID 19272130, 2009). "This phenomenon is consistent with previous findings that tumor cells secrete many immunosuppressive cytokines and chemokines (IL-6, IL-10, and TGF-β)." (PMID 18793383, 2008). "Partial maturation of DCs by tumor-derived factors like IL-10, vascular endothelial growth factor (VEGF), and TGF-β induces self-tolarence and promotes conversion of naive T cells to regulator T cells,favoring development of suppressive T cells." (PMID 19009040, 2008). "It has been demonstrated that tumor-associated fibroblasts and macrophages synthesize proteins, such as VEGF, TGF-β, and IL-10, all of which contribute to the local immunosuppressive environment." (PMID 18793383, 2008). "TLRsignaling on pDCs can be used to induce type I IFNs and possibly protect DCsfrom tumor-derived inhibitory factors (such as VEGFβ or IL-10), as well as supportT-cell survival, therefore, improving vaccination efficacy." (PMID 19190769, 2008). "Alternatively, IL-10 can inhibit the growth of new vessels within the tumor by acting on the tumor cells and indirectly by influencing infiltrating immune cells." (PMID 19040745, 2008). "In response to IL-12, Tcells polarize to Th1 and enhance CD8+ cytotoxic T-cell responseagainst tumor cells or pathogens, while IL-4- and IL-10-activated Th2 cellspromote humoral immune response and/or tolerance." (PMID 19009040, 2008). "It has been demonstrated that immune balance controlled by cytokines such as IL-10 and IL-12 plays an important role in immune regulation, including anti-tumor immunity." (PMID 19578511, 2008). "BesidesVEGF, other cytokines secreted by tumor cells are involved in the inhibition ofDC differentiation and maturation, among others are IL-6, IL-10, and M-CSF." (PMID 18320010, 2007). "Most of the cytokines that were preferentially present in ER-negative tumours (IL-1β, IL-6, IL-8, IL-10, IL-12, MCP-1 and MIP-1β) were also more abundant in high-grade tumours." (PMID 17261184, 2007).